MIR4769 (microRNA 4769)
Synonyms: hsa-mir-4769
Gene: MicroRNA gene on chromosome X (47,587,429 to 47,587,505, forward strand). Ensembl gene ENSG00000263858.
Diseases named in the same sentence as MIR4769 in open-access papers:
MIR4769 is named in the same sentence as 1 disease in open-access papers, as found by Europe PMC text mining. Sharing a sentence is not in itself a finding about the gene and the disease.
MIR4769 shares sentences with these, for which no sentence is quoted: Obesity (1 paper).